TSC22D3 (TSC22 domain family member 3)
Description:
Protects T-cells from IL2 deprivation-induced apoptosis through the inhibition of FOXO3A transcriptional activity that leads to the down-regulation of the pro-apoptotic factor BCL2L11. In macrophages, plays a role in the anti-inflammatory and immunosuppressive effects of glucocorticoids and IL10. In T-cells, inhibits anti-CD3-induced NFKB1 nuclear translocation and thereby NFKB1 DNA-binding activities. In vitro, suppresses AP-1 transcription factor complex DNA-binding activities (By similarity). [Isoform 1]: Inhibits myogenic differentiation and mediates anti-myogenic effects of glucocorticoids by binding and regulating MYOD1 and HDAC1 transcriptional activity resulting in reduced expression of MYOG.
Synonyms: hDIP; GILZ; TSC-22R; DSIPI; DIP
Tractability: PROTAC: ubiquitination databases record sites on it.
Gene: Protein-coding gene on chromosome X (107,713,221 to 107,777,342, reverse strand). Ensembl gene ENSG00000157514.
Subcellular location: Cytoplasm (Isoform 1); Nucleus
Subcellular location (Human Protein Atlas): Cytosol; Golgi apparatus; Nuclear speckles
Pathways (Reactome):
Transport of small molecules: Stimuli-sensing channels
Gene Ontology:
Molecular function: protein binding
Biological process: negative regulation of activation-induced cell death of T cells; regulation of transcription by RNA polymerase II
Cellular component: cytoplasm; cytosol; nucleus
Homologues: Orthologues: chimpanzee TSC22D3 (99% identical), macaque TSC22D3 (99% identical), rabbit TSC22D3 (95% identical), dog TSC22D3 (94% identical), guinea pig TSC22D3 (94% identical), mouse Tsc22d3 (88% identical), tropical clawed frog tsc22d3 (76% identical), pig TSC22D3 (60% identical), zebrafish zgc:64189 (51% identical), rat Tsc22d3 (46% identical), Caenorhabditis elegans Y48C3A.12 (32% identical), Drosophila melanogaster bun (30% identical), and 1 more. Paralogues in human: TSC22D1 (46% identical), TSC22D2 (40% identical), TSC22D4 (39% identical).
Diseases named in the same sentence as TSC22D3 in open-access papers:
TSC22D3 is named in the same sentence as 148 diseases in open-access papers, as found by Europe PMC text mining. Sharing a sentence is not in itself a finding about the gene and the disease. The quoted sentences say what the papers report.
colitis (25 papers, 2012 to 2025). Inflammation of the colon. "While TSC22D3 is commonly regarded as an anti-inflammatory therapeutic protein, reduced TSC22D3 expression has been reported to increase the release of pro-inflammatory factors and thus contribute to the development of inflammatory conditions such as colitis or liver fibrosis." (PMID 38036512, 2023).
Sepsis (13 papers, 2018 to 2024). Sepsis is defined as life-threatening organ dysfunction caused by a dysregulated host response to infection. "A last example illustrating the importance of GR complex formation to protect against sepsis is Tsc22d3 encoding Glucocorticoid Induced Leucine Zipper (GILZ)." (PMID 35203332, 2022). "However, this study identified the SNP rs3747406 in the TSC22D3 gene encoding the GILZ as a potential marker for predicting 30-day mortality in sepsis, depending on the SOFA Score." (PMID 38612684, 2024). "The glucocorticoid system and the intermediate TSC22D3 gene product—glucocorticoid-induced leucine zipper—are clinically relevant in sepsis, which is why this study aimed to clarify whether TSC22D3 gene polymorphisms contribute to the variance in sepsis mortality." (PMID 38612684, 2024). "Taken together, the data suppose that anti-inflammatory genes requiring an intact GR dimerization potential (i.e., Dusp1, SphK1 and Tsc22d3) are essential to transmit the protective effects of GR in SIRS and sepsis." (PMID 35203332, 2022). "In addition, GILZ, a TSC22D3 gene product, is identified as a promising protein for sepsis survival in a mouse model." (PMID 39135180, 2024). "In order to find candidate genes that can shed light on the variability in sepsis mortality, this study focused on the TSC22D3 gene and its product GILZ as one of the key glucocorticoid mediators, which has been considered a promising protein for sepsis survival in mouse models." (PMID 38612684, 2024). "Gene ontology of these 23 common DEGs showed that apoptotic process (TRAF1, TNFRSF9, ADORA2A, ZBTB16), negative regulation of transcription (SAP30, TSC22D3, ETS2, ZBTB16), and inflammatory response (TNFRSF9, CCL3, ADORA2A) are the main biological processes affected by sepsis treatment." (PMID 30086151, 2018).
psoriasis (12 papers, 2015 to 2025). An autoimmune condition characterized by red, well-delineated plaques with silvery scales that are usually on the extensor surfaces and scalp. "The decrease in TSC22D3 mRNA and protein levels is associated with an increase in inflammation severity in systemic lupus erythematosus (SLE), ulcerative colitis, psoriasis, and other autoimmune inflammatory diseases." (PMID 41262126, 2025). "Additional shared signatures between ILCs and T cells were related to genes that regulate tissue residency (FOS and NR4A1; module 18) as well as quiescence (TSC22D3, DUSP1, ZFP36L2, and KLF6; module 22), the latter recently shown to be expressed by plastic skin ILCs in a mouse model of psoriasis." (PMID 37160121, 2023).
rheumatoid arthritis (11 papers, 2014 to 2024). A chronic, systemic autoimmune disorder characterized by inflammation in the synovial membranes and articular surfaces. "IPA of annotated transcripts showed similar activation of osteogenic-associated pathways such as roles of osteoblasts, osteoclasts, and chondrocytes in rheumatoid arthritis as well as the expression of typical osteogenic genes such as dlx5, tsc22d3, alpl, klf4, ext1, and stc1 in both datasets." (PMID 30376879, 2018).
melanoma (9 papers, 2016 to 2025). A malignant, usually aggressive tumor composed of atypical, neoplastic melanocytes. "In agreement with the relatively quiescent state of H2B-GFP label-retaining human MeSCs31, 32, TSC22D3 was significantly down-regulated in the FACS-sorted GFPhigh subpopulation of human melanoma HBL-H2B-GFP cells." (PMID 27465291, 2016). "Cell cycle analysis of HBL H2B-GFP cells transiently transfected with human TSC22D3-specific siRNA demonstrated that, similar to mouse cells, the proportion of human melanoma cells entering the G0 phase of the cell cycle was increased with GILZ down-regulation." (PMID 27465291, 2016).
depression (8 papers, 2016 to 2024). "Further examples include the hypoxia inducible factor 3 alpha subunit (Hif3a), whose expression was found to be increased in schizophrenic and bipolar patients or Sgk1 and Tsc22d3, which were associated with high interleukin (IL)-6 levels in patients suffering from the major depressive disorder." (PMID 27188165, 2016). "IFN I type, an increase in which is also found in depression, can induce GC resistance in interferopathies through reduced expression of glucocorticoid-induced leucine zipper protein (GILZ) (TSC22D3 gene)." (PMID 38067176, 2023). "TSC22D3 is induced by stress levels of glucocorticoids and encodes a leucine zipper protein linked to MAPK signaling and neuroplasticity in depression." (PMID 29096718, 2017). "However, brain Tsc22d3 is not increased in conditions that are associated with chronic glucocorticoid activation, such as chronic stress and major depressive disorder." (PMID 35458399, 2022).
liver fibrosis (6 papers, 2021 to 2025). "The expression of TSC22D3 in liver biopsy samples of patients with liver fibrosis is negatively correlated with the expression of CCL2." (PMID 41262126, 2025).
colorectal cancer (5 papers, 2021 to 2025). A primary or metastatic malignant neoplasm that affects the colon or rectum. "Psychological distress is reported to induce the elevation of plasma corticosterone and expression of glucocorticoid-inducible factor Tsc22d3, which blocks type I interferon responses and subverts therapy-induced anticancer immunosurveillance in colorectal cancer and non–small cell lung carcinoma." (PMID 36918865, 2023).
Infertility (5 papers, 2012 to 2023). "TSC22D3-deficient males were infertile and exhibited severe testicular dysplasia and a high number of apoptotic cells within the seminiferous tubules." (PMID 36980830, 2023).
lung carcinoma (5 papers, 2012 to 2025). "Studies have shown that stress-induced glucocorticoid surges and Tsc22d3 upregulation can interfere with treatment-induced immune surveillance and that glucocorticoid use after immune checkpoint inhibitors may alleviate lung-cancer-related symptoms." (PMID 40017690, 2025). "Hence, our findings demonstrate that site-specific RBM47-ISGylation mediated by a chimeric E3 ligase diminishes TSC22D3 expression in various cell types, such as immune cells and human lung cancer cells." (PMID 38036512, 2023). "Our findings demonstrate that RBM47-ISGylation inhibits the expression of TSC22D3 in human cells, including lung cancer cell lines and the T lymphocyte line Jurkat, demonstrating that human RBM47-ISGylation has a consistent function, as confirmed by mouse models." (PMID 38036512, 2023). "Recent studies have demonstrated that TSC22D3 can impair immune responses by inhibiting the type I interferon responses in dendritic cells and activation of IFN-γ + T cells, which hinders the anticancer immunosurveillance and immunotherapy of lung cancer." (PMID 38036512, 2023).
osteoporosis (5 papers, 2014 to 2025). A condition of reduced bone mass, with decreased cortical thickness and a decrease in the number and size of the trabeculae of cancellous bone (but normal chemical composition), resulting in increased fracture incidence. "In patients with long-term use of glucocorticoids, the expression of TSC22D3 may become an indicator for evaluating the risk of osteoporosis, helping doctors assess bone health status and take corresponding intervention measures." (PMID 41262126, 2025). "TSC22D3 is induced to express under the action of glucocorticoids and may indirectly affect bone metabolism by regulating inflammatory responses, cell proliferation, and other processes, especially in regulating bone diseases caused by glucocorticoids such as osteoporosis." (PMID 41262126, 2025).
Anxiety (3 papers, 2019 to 2025). Intense feelings of nervousness, tension, or panic often arise in response to interpersonal stresses. "In murine models, anxiety-like behaviors induced by social defeat are associated with diminished antitumor efficacy, linked to elevated plasma corticosterone levels and upregulation of the glucocorticoid-responsive transcription factor TSC22 domain family member 3 (Tsc22d3)." (PMID 41163091, 2025).
cervical carcinoma (3 papers, 2023 to 2025). A carcinoma arising from either the exocervical squamous epithelium or the endocervical glandular epithelium. "In the bioinformatics analysis of cervical cancer-related genes, TSC22D3 has significant features in the cell proliferation signaling system." (PMID 41262126, 2025). "Consequently, the expression levels of JUN and TSC22D3 in cervical cancer tissues displayed an overall downward trend compared with non-tumor tissues." (PMID 37187896, 2023). "In addition, the expression of four genes, including JUN, TSC22D3, DUOX1, and HELLS, in cervical cancer tissues was verified by qRT-PCR." (PMID 37187896, 2023).
COVID-19 (3 papers, 2023 to 2024). A disease caused by infection with severe acute respiratory syndrome coronavirus 2. "Furthermore, our findings showed that other genes, including TSC22D3, DUSP-1, JAK-1, and MAPK-1 expressions, were significantly elevated in mild COVID-19." (PMID 38187222, 2024).
diabetes (3 papers, 2020 to 2023). "TSC22D3 inhibits hypoxia- and diabetes-induced galectin-1 expression due to hypoxia and diabetes by disrupting the stability of the HIF-1α protein." (PMID 36466094, 2022). "In vivo, glucocorticoids injected into murine eyes decreased diabetes‐induced retinal galectin‐1 and TSC22D3 expression and HIF‐1α protein up‐regulation." (PMID 32150332, 2020). "Glucocorticoid treatment to mice significantly alleviated diabetes‐induced retinal HIF‐1α and galectin‐1/Lgals1 levels, while increasing TSC22D3 expression." (PMID 32150332, 2020).
heart failure (3 papers, 2021 to 2024). Inability of the heart to pump blood at an adequate rate to meet tissue metabolic requirements. "We found that the four core genes (Tsc22d3, Itga6, Ermn, Sult1a1) were associated with immune system diseases, drug-related side effects and adverse reactions, chemical and drug-induced liver injury, neurological disorders, heart failure, mental disorders, and neural tube defects." (PMID 38843390, 2024). "Klf4, Gas6, and Tsc22d3 showed consistent up-regulation at all timepoints studied post-MI in the adult mouse heart, and in both types of heart failure in human patients." (PMID 36082978, 2023).
Obesity (3 papers, 2009 to 2023). Accumulation of substantial excess body fat. "Some genes in this subnetwork, such as Arntl, Dbp, Per1, and Per2, are known to associate with obesity traits, while other genes, such as Map3k6 and Tsc22d3, represent novel factors." (PMID 19463160, 2009).
allergic disease (2 papers, 2023 to 2025). An immune response that occurs following re-exposure to an innocuous antigen, and that requires the presence of existing antibodies against that antigen. "More importantly, the NK cells with TSC22D3 deficiency promoted CD8+ T cell responses and a shift from promoting proliferation of CD4+ T to CD8+ T cells, implying an important role for the innate immune system in regulating drug-induced allergic disease." (PMID 40544157, 2025).
Cushing syndrome (2 papers, 2021 to 2023). Cushing's syndrome (CS) encompasses a group of hormonal disorders caused by prolonged and high exposure levels to glucocorticoids that can be of either endogenous (adrenal cortex production) or exogenous (iatrogenic) origin. "Tsc22d3 is also one of the most regulated genes in Cushing’s syndrome (CS) and has been demonstrated to regulate osteoblast and bone turnover." (PMID 34765608, 2021).
Hypertension (2 papers, 2014 to 2021). The presence of chronic increased pressure in the systemic arterial system. "‘Unknown I’ contained a diverse set of key driver genes such as SGK1, SIK1 and SLC10A6 (sodium metabolism and hypertension), MT2A and TSC22D3 (glucocorticoid signaling), GADD45G, ERRFI1, GPRC5A, and EGFR (cell growth and apoptosis), and CEBPB, CEBPD, and KCNA5 (heart development and function)." (PMID 25033284, 2014).
leukemia (2 papers, 2007 to 2023). A malignant (clonal) hematologic disorder, involving hematopoietic stem cells and characterized by the presence of primitive or atypical myeloid or lymphoid cells in the bone marrow and the blood. "MIR143-3p sponging TSC22D3 might have anti-leukemia effect in adult AML." (PMID 37237254, 2023).
adenoma (1 paper, 2024). A neoplasm arising from the epithelium. "As observed with NR3C1, TSC22D3 transcripts are reduced in adenoma versus normal tissue but further induced at the adenoma-to-carcinoma progression; they strongly correlate with PRNP levels, including in the large GSE39582 dataset and are enriched in CMS4 CRC." (PMID 38589873, 2024).
chlamydia (1 paper, 2024). "The another glucocorticoid-responsive gene TSC22D3 (GILZ) is found to be differentially expressed under gonorrhea or chlamydia exposure based on many animal and human gene studies that examine different cell types." (PMID 39018275, 2024).
hepatoma (1 paper, 2013). "Next, ChIP-Seq analysis, studying the binding of GR to DNA upon dexamethasone (Dex) stimulation of mouse hepatoma cells, identified Tsc22d3 as the only GC-inducible gene in this QTL region." (PMID 23495141, 2013).
herpesvirus infection (1 paper, 2025). "Given the impact of PAQR3 knockdown on TSC22D3, we also observed that differentially expressed genes were enriched in the Herpes simplex virus 1 infection, Human T-cell leukemia virus 1 infection, Human immunodeficiency virus 1 infection, and Kaposi sarcoma-associated herpesvirus infection pathways." (PMID 40723340, 2025).
human papillomavirus infection (1 paper, 2025). "GO analysis of TSC22D3 highlighted its role in osteogenic differentiation, while pathway analysis linked it to human papillomavirus infection, cytoskeleton regulation, and WNT signaling." (PMID 41262126, 2025).
liver steatosis (1 paper, 2020).
myeloid leukemia (1 paper, 2023). A clonal proliferation of myeloid cells and their precursors in the bone marrow, peripheral blood, and spleen. "DO analysis revealed that TSC22D3 was involved in tumors, including myeloid leukemia." (PMID 37237254, 2023).
ocular hypertension (1 paper, 2025). Abnormally high intraocular pressure. "Glucocorticoids can alter TSC22D3 gene expression, influencing macrophage activity and potentially affecting trabecular meshwork microstructure, thereby causing ocular hypertension." (PMID 40996982, 2025).
post-traumatic stress disorder (1 paper, 2021). An anxiety disorder precipitated by an experience of intense fear or horror while exposed to a traumatic (especially life-threatening) event. "In a nice translational study, blood mRNA expression of the gene GC-induced leucine zipper (GILTZ encoded by Tsc22d3 gene) was found decreased in subjects with post-traumatic stress disorder (PTSD), and especially in those that presented traumatic events in childhood, both in males and females." (PMID 33808655, 2021).
septic peritonitis (1 paper, 2020). Septic peritonitis is an inflammatory condition of the peritoneum that occurs secondary to microbial contamination. "On the contrary, overexpression of TSC22D3 successfully protected mice against a lethal form of septic peritonitis." (PMID 32630206, 2020).
sterility (1 paper, 2016). "Our extensive validation has not revealed any evidence of leakiness, that is, of hemizygous Tsc22d3 knockout germ cells producing fertile spermatozoa; the sterility is due to a cell‐autonomous defect in spermatogenesis that is extremely stringent." (PMID 27012318, 2016).